DNMT1 (DNA methyltransferase 1)
Diseases named in the same sentence as DNMT1 in open-access papers (continued):
Sharing a sentence is not in itself a finding about the gene and the disease.
melanoma (continued). "This study demonstrated that TIP60 and USP7 downregulation decreases ac-DNMT1 protein levels, which increased the amount of DNMT1 and significantly influenced stage IV melanoma disease outcomes." (PMID 34572918, 2021). "To further validate the observation of the increased DNMT1 expression in melanoma, we performed IHC for DNMT1 on our SJCI-established TMA sections that contained melanoma and normal organ FFPE tissues." (PMID 34572918, 2021). "To date, limited studies have investigated the expression of DNMT1 in melanoma patients and disease outcomes." (PMID 34572918, 2021). "Taken together, our studies demonstrated ac-DNMT1 is a promising melanoma prognostic factor for predicting MSS." (PMID 34572918, 2021). "The decreased expression levels of TIP60 or USP7 were associated with melanoma progression, which suggested these two proteins play an important role in modulating the levels of ac-DNMT1 in melanoma metastasis." (PMID 34572918, 2021). "A significant correlation was found between ac-DNMT1 protein levels with disease outcomes status in stage IV melanoma patients." (PMID 34572918, 2021). "Panobinostat treatment enhanced ac-DNMT1 protein levels with a concomitant reduction in DNMT1 protein levels in both melanoma cell lines." (PMID 34572918, 2021). "Kaplan–Meier and multivariate Cox proportional hazard analysis revealed that ac-DNMT1 protein level is a significant independent prognostic factor for 4-year MSS in stage IV melanoma patients." (PMID 34572918, 2021). "The Kaplan–Meier analysis showed that low ac-DNMT1 protein levels are associated with shorter 4-year MSS (p = 0.006, log-rank test) in stage IV melanoma patients." (PMID 34572918, 2021). "Among stage IV melanoma, patients with low ac-DNMT1 protein levels showed significantly lower USP7 protein levels compared to patients with high ac-DNMT1 (p < 0.0001)." (PMID 34572918, 2021). "Assessment of nevus, primary melanoma, and melanoma metastasis show that DNMT1 expression is enhanced with melanoma progression and positively correlates with the Ki-67 levels." (PMID 34572918, 2021). "Up to 63% (74 of 117) of the melanoma patients who expired had low ac-DNMT1 protein levels, while 33% (8 of 24) of the alive patients had low ac-DNMT1 protein levels (p = 0.007, χ2 test)." (PMID 34572918, 2021). "Tissues from stage III and IV melanoma patients showed reduced protein levels of ac-DNMT1 and consequently enhanced protein expression of DNMT1 compared to primary melanoma tumors and normal organ control tissues." (PMID 34572918, 2021). "Multivariate analysis indicated that ac-DNMT1 protein level was an independent factor for melanoma-specific survival (MSS)." (PMID 34572918, 2021). "The DNMT3 family plays an important role in melanoma tumor progression; however, the role of DNMT1 is less understood." (PMID 34572918, 2021). "DNA methyltransferase 1 (DNMT1) mediated methylation of TRPM1/MIR211 promoter reduces MIR211 expression levels in melanoma cells." (PMID 33628737, 2020). "Methylation of DcR1 promoter was demonstrated in malignant melanoma cells to require the DNA methyl transferase DNMT1, whereas DcR2 methylation involved both DNMT1 and DNMT3a." (PMID 31248188, 2019). "Cancer-germ line gene activation upon DNMT1 transient depletion was observed in 45 human melanoma cell lines using a microarray approach." (PMID 28396701, 2017). "miR-211 expression is regulated by DNA methylation (DNMT1) in melanoma and can act as a metabolic switch through regulating HIF-1a protein stability and inhibiting EMT by targeting RAB22A." (PMID 28396701, 2017). "One possible mechanism for V600EBRAF driven gene hypermethylation in melanoma cells is via upregulation of DNA methyltransferase 1 (DNMT1)." (PMID 29179510, 2017). "Azaciticine (VidazaTM) and Decitabine (Dacogen®), which are the DNMT-1 inhibitors, have been approved for treating myelodysplastic syndromes; the drugs are still in clinical trial for melanoma treatment." (PMID 29100458, 2017).
melanoma (continued). "Our data indicate that, at least in melanoma, activation of CG genes is due to a phase of DNMT1 depletion." (PMID 26504497, 2015). "Treatment of melanoma cells with decitabine, a Dnmt1 inhibitor, induced differentiation of these cells and inhibited tumor growth in vivo in a mouse melanoma model." (PMID 27158195, 2015). "Consistently, analysis of a large set of melanoma tissues revealed that DNMT1 expression levels were often lower in samples showing activation of multiple CG genes." (PMID 26504497, 2015). "A major perspective will be to uncover the mechanisms that are responsible for the phase of DNMT1 depletion in melanoma cells." (PMID 26504497, 2015). "This analysis revealed lower DNMT1 expression levels in melanoma samples showing activation of multiple CG genes." (PMID 26504497, 2015). "To this end, we compared the level of DNMT1 expression in melanoma tissue samples displaying either little or extensive activation of CG genes." (PMID 26504497, 2015). "Cellular senescence, which was shown to constitute an early (but escapable) barrier to melanoma development, represents therefore a possible origin to the phase of DNMT1 depletion." (PMID 26504497, 2015). "In summary, our present study provides in vivo evidence that aberrant activation of CG genes in melanoma is the result of a past event of DNMT1 depletion." (PMID 26504497, 2015). "The difference in global methylation levels and protein expression of DNMT1 and DNMT3b prompted us to investigate the methylation profiles of the proliferative and invasive phenotype melanoma cells." (PMID 25885555, 2015). "In the present study, we investigated the possibility that CG gene activation in melanoma is the result of an episode of DNMT1 depletion." (PMID 26504497, 2015). "This suggests that part of the analyzed melanoma tissue samples were still undergoing the process of DNMT1 depletion at the time they were removed, and many of these samples also expressed CG genes." (PMID 26504497, 2015). "We observed that the invasive phenotype melanoma cell cultures had about 51.1% less expression of DNMT1 as compared to the proliferative phenotype melanoma cell cultures." (PMID 25885555, 2015). "One possible explanation for the persistent repression of CDCA7L in melanoma cells was that DNMT1 depletion led to the irreversible activation of a factor that imposes silencing of the gene." (PMID 26504497, 2015). "The DNA CN alterations of DNMT1 in advanced stages primary melanomas raise crucial questions: Is demethylation, contributing to clinical outcomes, only a passive consequence of CN loss?" (PMID 24832207, 2014). "The suppression of DNMT1 reversed interferon-mediated apoptosis resistance in melanoma cells." (PMID 39935431, 2025). "So DNMT1‐mediated promoter methylation functions to suppress miRNA activity within melanoma." (PMID 40387409, 2025). "Therefore, the DNMT1/miR‐211/RAB22A axis offers a fresh perspective on the aetiology of melanoma, specifically concerning its involvement in the EMT pathway." (PMID 40387409, 2025). "Besides, analysis of Cancer Dependency Map dataset also validated DNMT1 knockout by CRISPR/Cas9 gives high essential gene score in the epigenetic targets across melanoma cell lines, featuring a critical role for DNMT1 in melanoma." (PMID 38874532, 2024). "We validated the DNMT1 overexpression in melanoma by TCGA dataset." (PMID 38874532, 2024). "Investigating the aberrant mechanisms that control DNMT1 activity during melanoma progression may improve our understanding of gene methylation during tumor progression." (PMID 34572918, 2021). "We then verified the results by performing IHC for ac-DNMT1 in the melanoma TMA." (PMID 34572918, 2021). "Additionally, we identified the positive correlations between TIP60/USP7 and ac-DNMT1 protein levels in stage IV melanoma metastasis." (PMID 34572918, 2021).
melanoma (continued). "In addition, we chose to study two major epigenetic regulators, DNMT1 (DNA methyltransferase 1) and EZH2 (enhancer of zeste homologue 2), since high levels of expression have been associated to melanoma aggressiveness." (PMID 30651148, 2019). "Decitabine has been shown to deplete DNMT1 after incorporation into the DNA in melanoma cell lines." (PMID 29179510, 2017). "Another possible explanation for the permanent repression of CDCA7L in melanoma cells was that down-regulation of this gene during the phase of DNMT1 depletion allowed local deposition of repressive epigenetic marks, which progressively locked the gene into an irreversible silent state." (PMID 26504497, 2015). "It remains possible, however, that tumors other than melanoma experience a phase of transient DNMT1 depletion, which in this case would not be associated with permanent acquisition of the gene expression signature we identified." (PMID 26504497, 2015). "These initial observations raised therefore the possibility that CG gene demethylation and activation in melanoma cells might be the consequence of a process of DNMT1 depletion." (PMID 26504497, 2015). "This explains why the gene expression signature could still be detected in melanoma cell lines, which otherwise showed restored DNMT1 expression levels." (PMID 26504497, 2015). "Thus, while this depletion process is still in progress in several melanoma tissues, DNMT1 expression levels are likely restored in most melanoma cell lines that were expanded in vitro." (PMID 26504497, 2015). "Thus, the EZH2/DNMT1/MIR211/RAB22A axis might provide novel insights into the molecular pathogenesis of both melanoma and glioblastoma, particularly on the EMT processes in these two different cancers." (PMID 33628737, 2020). "This may be due to decreased DNMT1 protein expression in the invasive phenotype melanoma cells." (PMID 25885555, 2015). "Tao reported that PRMT1 acts as an inhibitor of CD8+ T-cell recruitment and activation in melanoma and that deletion of PRMT1 reduces the abundance of H3K27ac and H4R3me2a in the Dnmt1 enhancer region, thereby reducing Dnmt1 expression in melanoma cells." (PMID 40858547, 2025). "To further interrogate the role of DNMTs in melanoma-STING silencing, we transfected B16-F10 cells with small interfering RNA (siRNA) targeting DNMT1, DNMT3A, and DNMT3B." (PMID 36949064, 2023). "There were significant positive correlations between TIP60 and ac-DNMT1 protein levels in tissues from both stage III (r = 0.59, p = 0.01) and stage IV (r = 0.6, p < 0.0001) melanoma patients." (PMID 34572918, 2021). "Most importantly, a significant inverse correlation was observed between ac-DNMT1 and DNMT1 protein levels in both stage III (r = −0.55, p = 0.02) and stage IV (r = −0.18, p = 0.02) melanoma patients." (PMID 34572918, 2021). "We therefore examined the USP7 protein levels to understand the relationship between DNMT1 and ac-DNMT1 as related to TIP60 and melanoma progression." (PMID 34572918, 2021). "The results demonstrated a significant reduction in ac-DNMT1 protein levels in metastatic melanoma (stage III mean H-score = 48, p = 0.006; stage IV mean H-score = 67, p = 0.03) compared to primary melanoma tissues (mean H-score = 144)." (PMID 34572918, 2021). "Ac-DNMT1 protein levels were significantly reduced in stage III (mean H-score = 41, p = 0.001) and stage IV (mean H-score = 65, p = 0.03) melanoma tissues compared to normal organ tissues (mean H-score = 91)." (PMID 34572918, 2021). "This study demonstrated that DNMT1 and ac-DNMT1 protein levels were inversely correlated in stage III (n = 17) and stage IV (n = 164) metastatic melanoma tumors, and both influenced melanoma progression." (PMID 34572918, 2021). "In this study, we assessed DNMT1 and acetylated-DNMT1 (ac-DNMT1) protein levels in AJCC stage III and IV melanoma patients as related to disease progression and in comparison to normal organ control tissues." (PMID 34572918, 2021).
melanoma (continued). "Most importantly, there were significant inverse correlations between ac-DNMT1 and Ki-67 protein levels in both stage III (r = −0.53, p = 0.03) and stage IV metastatic melanoma tissues (r = −0.18, p = 0.02)." (PMID 34572918, 2021). "Of clinical translational relevance, patients with high ac-DNMT1 protein levels, or high-acDNMT1 with concurrent low DNMT1, high TIP60, or high USP7 protein levels showed significantly better prognosis for 4-year melanoma-specific survival." (PMID 34572918, 2021). "TIP60 mRNA downregulation during melanoma progression explains the reduction in TIP60 protein levels and the consequent reduction in ac-DNMT1 protein levels observed in metastatic melanoma." (PMID 34572918, 2021). "In melanoma cells, detachment from the plating surface revealed an increase in ROS, including H2O2, as well as an increase in global DNA methylation and Dnmt1 expression." (PMID 31215478, 2019). "The highly methylated environment in human melanoma cell lines (e.g., SkMel-28) has been reported, and both COMT (Cathechol O-methyl transferase) and DNA methyltransferase-1 were found to be increased approximately five and eight times, respectively." (PMID 21079799, 2010). "Antisense depletion of DNMT1 in the MZ2-MEL cell lines was shown to lead to hypomethylation and re-expression of the germ line-specific MAGE-A1 transgene, which is commonly silenced in melanoma." (PMID 28396701, 2017). "Whereas we uncovered an epigenetically fixed gene expression signature in melanoma cells attesting their transition through an episode of DNMT1 depletion, no similar gene expression signature was observed in other tumor types." (PMID 26504497, 2015). "Additionally, SNPs in DNMT1 (rs2228612, rs2228611, and rs2114724) and DNMT3B (rs406193 and rs2424932) have been shown to affect the clinical course and disease outcome in patients with melanoma." (PMID 33024276, 2020). "Lack of such a correlation in melanoma cell lines may be related to the transient nature of the DNMT1 depletion process." (PMID 26504497, 2015). "In agreement with this hypothesis, we have recently shown that curcumin inhibited melanoma cell proliferation and cell cycle progression by accumulating cells at the G2/M-phase with decreased expression of UHRF1 and DNMT1 and enhanced expression of p21, a p16INK4A -homolog." (PMID 23688286, 2013).
atherosclerosis (54 papers, 2014 to 2026). A disease characterized by the build-up of fatty material and calcium deposition in the arterial wall resulting in partial or complete occlusion of the arterial lumen. "Mutual regulation between miR-148a/152 and DNMT1 in foam cells probably plays a critical role in the pathogenesis of atherosclerosis, which underlines the potential of its use in therapy." (PMID 31212708, 2019). "This is in line with a study that investigated the effect of hyperlipidemia and hyperhomocysteinemia on atherogenesis in ApoEo mice and found that increased atherosclerosis was associated with global DNA hypomethylation, decreased DNMT1 gene expression and activity." (PMID 37153468, 2023). "Since increased DNMT expression was associated with increased cellular proliferation in atherosclerosis, we speculate that the DNMT1 expression levels might be altered under different genotypes which then contributes to the pathological process of CAD." (PMID 25493477, 2014). "Moreover, this presented study may facilitate the establishment of a causal relationship between expression of endothelial DNMT1 and the pro-atherogenic endothelial dysfunction and offer opportunities for therapeutic intervention of atherosclerosis." (PMID 29118325, 2017). "Our results reveal that Aza converts naive CD4+ T cells into functional Tregs by inhibiting Dnmt1, and the transfer of Aza-iTregs suppresses atherosclerosis in mice." (PMID 39304654, 2024). "The DNMT inhibitor RG108 is instrumental in addressing atherosclerosis and coronary heart disease through its ability to inhibit the activities of DNMT1 and DNMT3a." (PMID 39458994, 2024). "Our findings demonstrate that iTregs can be epigenetically edited ex vivo by using the Aza-based approach through the inhibition of Dnmt1, and that Aza-iTregs can suppress atherosclerosis in vivo." (PMID 39304654, 2024). "Conversely, patients with atherosclerosis have increased expression of DNMT1 and pro-inflammatory cytokines with decreased PPAR-γ expression." (PMID 37947606, 2023). "Inhibiting DNMT1-dependent methylation of the estrogen receptor α (ERα) gene increases ERα expression and prevents post-menopausal atherosclerosis and homocysteine-induced endothelial cell apoptosis in mice." (PMID 37947606, 2023). "Overexpression of DNMT1 in macrophages significantly increases pro-inflammatory cytokine production and accelerates atherosclerosis in ApoE KO mice." (PMID 37947606, 2023). "In the atherosclerosis model, the increased expression of DNMT1 in human umbilical vein endothelial cells (HUVECs) leads to the apoptosis of endothelial cells." (PMID 37822364, 2023). "Endothelial-specific knockout of Dnmt1 protected the vasculature from disturbed flow-induced remodeling and atherosclerosis." (PMID 37649604, 2023). "In contrast to DNMT3a, the overexpression of Dnmt1 promotes proinflammatory cytokine production in macrophages and plasma during atherosclerosis and inflammation." (PMID 37929702, 2023). "By using the EC-specific Dnmt1 mutant mice, our study has added a determinant piece of evidence for validation of the role of Dnmt1 in mediating EC dysfunction and atherosclerosis." (PMID 37649604, 2023). "DNMT1 and DNMT3a are two major DNMTs in ECs that direct the methylation of genes or signaling molecules to modulate aortic disorders, such as atherosclerosis." (PMID 36293392, 2022). "Another preclinical study found that there is a reciprocal regulation between miR-148a/152 and DNMT1 in Hcy-accelerated atherosclerosis." (PMID 36293305, 2022). "In line with this, several studies have reported that DNMT1 and DNMT3a-dependent DNA methylation altered the blood flow, inducing atherosclerosis in murine models via modifications of transcriptional factors." (PMID 35563540, 2022).